THAP1 (THAP domain containing 1)
Diseases named in the same sentence as THAP1 in open-access papers (continued):
Sharing a sentence is not in itself a finding about the gene and the disease.
Dystonia (continued). "The broad clinical heterogeneity of THAP1 dystonia and low penetrance of known coding variants suggest that noncoding variants in THAP1 could contribute to the risk of developing adult-onset primary dystonia." (PMID 24936516, 2014). "However, the reduced penetrance of some monogenic forms of dystonia, such as those due to mutations in TOR1A and THAP1, means that many apparently sporadic cases may also fall into this category." (PMID 23775978, 2013). "Notably, PSMB5 overexpression was sufficient to rescue the cellular phenotype, raising important questions: could genetic variation in proteasome-related genes act as a protective factor, thereby contributing to the well-recognized incomplete penetrance in THAP1-related dystonia?" (PMID 41518464, 2026). "The most frequently implicated genes included the well‐established isolated and combined dystonia genes VPS16 (n = 17 index patients), THAP1 (n = 14), GCH1 (n = 13), SGCE (n = 12), GNAL (n = 8), and KMT2B (n = 8)." (PMID 40533913, 2025). "The disruption of THAP1 function impairs its regulatory control over TOR1A, potentially contributing to dystonia pathogenesis through a shared molecular pathway." (PMID 40724495, 2025). "However, as none of these genes are currently associated with dystonia and aberrant proteostasis is a feature of many neurological disorders, these data highlight proteasome dysfunction as a candidate pathogenic mechanism underlying THAP1 dystonias." (PMID 39929834, 2025). "We observed convergence among dystonia genes toward either strong bursts or tonic behavior, with SGCE and THAP1 exhibiting opposite behaviors." (PMID 40062447, 2025). "First, the identification of THAP1 as a critical activator of PSMB5 expression suggests that proteasome dysfunction could underlie the pathogenesis of DYT-THAP1, although, to the best of our knowledge, no other mutations in proteasome genes have so far been associated with dystonia." (PMID 39929834, 2025). "An identical pattern of combined putaminal and pallidal hypometabolism was seen in two genetic subcategories (THAP1 and GCDH/GA-1); these conditions manifest with dystonia distinguishable on clinical grounds but are often treatment-resistant." (PMID 36445406, 2023). "A genetic etiology was identified in 17 patients [eight harboring TOR1A (DYT1), five harboring THAP1 (DYT6), and four harboring KMT2B (DYT28)] while the rest had idiopathic dystonia (n = 16)." (PMID 32322234, 2020). "We sequenced THAP1 exons 1, 2 and 3 including exon-intron boundaries and 5’UTR fragment in 96 non-DYT1 dystonia patients." (PMID 26087139, 2015). "Finally, leveraging a phenotypic assay to systematically assess the activity of THAP1 mutants at the endogenous PSMB5 locus, we define the transcriptional activity of THAP1 mutants found in dystonia patients." (PMID 39929834, 2025). "Therefore, given the previous evidence suggesting a role of eIF2a signaling dysregulation in dystonia, and our own RNA-seq data, we investigated UPR genes and proteins to assay the baseline status of the UPR in Thap1 recombinant mice." (PMID 29364887, 2018). "However, in practice, this has not happened and both clinicians and researchers alike tend to use dystonia loci and genes names interchangeably, e.g. DYT1/TOR1A or DYT6/THAP1." (PMID 23775978, 2013). "Hence, we may be unable to detect disease-relevant genetic interactions of DYT genes that are likely to generate dystonia through a fundamental role during brain development, such as TOR1A, THAP1 and KMT2B." (PMID 32889528, 2020). "The genetic background of DYT6 dystonia is additionally obscured by a low mutation frequency: at least 75% of patients screened in different studies, showing symptoms corresponding to DYT6 phenotype, harbor no THAP1 mutations." (PMID 26087139, 2015).
Dystonia (continued). "Sequencing of the other known PTD genes (THAP1, TUBB4a, CIZ1, ANO3, and GNAL) should be considered in patients with predominant cranial-cervical and laryngeal involvement, especially if family history is positive, with prioritization according to the age at onset and distribution of dystonia." (PMID 23596437, 2013). "An underlying unknown genetic cause is suggested by a study whereby 36 of 185 patients with musician’s dystonia had a family history of task-specific dystonia, yet the patients with a positive family history screened negative for DYT1 and THAP1 mutations, except for 2 patients with early onset MD." (PMID 23814536, 2013). "Using a principal component analysis approach to identify a specific dystonia-related metabolic pattern (DYT-RP) revealed, not surprisingly, an increased DYT-RP expression in TOR1A and THAP1 MCs and a reduced expression in NMCs even when compared to controls." (PMID 33486625, 2021).
generalized dystonia (7 papers, 2012 to 2024). "DYT6 dystonia belongs to a group of isolated, genetically determined, generalized dystonia associated with mutations in the THAP1 gene." (PMID 36096774, 2022).
Parkinsonism (6 papers, 2015 to 2025). Characteristic neurologic anomaly resulting from degeneration of dopamine-generating cells in the substantia nigra, a region of the midbrain, characterized clinically by shaking, rigidity, slowness of movement and difficulty with walking and gait. "Variants in none of the five implicated dystonia genes (TOR1A, SGCE, GNAL, THAP1 and KMT2B) have been reported to cause PD/parkinsonism to date." (PMID 39087914, 2024). "Moreover, three signals involved the THAP1 gene set (paired with Alzheimer’s disease, ALS and viral infection) and four involved the SETX gene set (paired with Alzheimer’s, Parkinson’s, Huntington’s and ALS)." (PMID 36271102, 2022).
idiopathic dystonia (4 papers, 2013 to 2025). "Seven (10%) patients had confirmed genetic diagnosis (including THAP1, ADCY5, VPS41, ATXN3, AFG3L2, KMT2B), 12 (18%) had acquired causes and the remainder had idiopathic dystonia." (PMID 34437382, 2021).
acute lymphoblastic leukemia (2 papers, 2015 to 2020). Leukemia with an acute onset, characterized by the presence of lymphoblasts in the bone marrow and the peripheral blood. "THAP1, a gene encoding a nuclear proapoptotic protein, could induce cellular apoptosis in acute lymphoblastic leukemia cells." (PMID 31537905, 2020). "A recent study reported that Par-4 (prostate apoptosis response factor-4) and THAP1, a sequence specific DNA binding factor, synergestically cooperate to enhance CARP-1/CCAR1 expression, and promote T-cell acute lymphoblastic leukemia cells (T-ALL) apoptosis." (PMID 25894788, 2015).
Dystonia-6 (2 papers, 2016 to 2025). "DYT-THAP1 (dystonia 6, DYT6, OMIM#602629) is an autosomal dominant disorder caused by heterozygous loss-of-function variants in THAP1, located on chromosome 8p21." (PMID 40724495, 2025). "Inherited isolated craniocervical dystonias are rare, and most commonly caused by pathogenic variants in THAP1 (Dystonia-6, DYT6, MIM# 602629) and GNAL (Dystonia-25, DYT25, MIM# 615073) and have adolescent to late adult onset with variable penetrance." (PMID 27919237, 2016).
myoclonus dystonia (2 papers, 2022 to 2024). "Thirteen studies explored genetically homogeneous cohorts, involving DYT1 (TorsinA mutation) (n = 3) and DYT6 (THAP1 mutation) (n = 1, or both n = 2), DYT3 (n = 2), X‐linked dystonia parkinsonism (DYT12, ATP1A3 mutation, n = 2), myoclonus dystonia (DYT11, SGCE mutation, n = 2) and DYT27 (n = 1)." (PMID 35785410, 2022). "Analysis of the TOR1A, THAP1, and SGCE genes excluded dystonia type 1, 6 (DYT1, DYT6) and myoclonus dystonia (DYT11)." (PMID 38916623, 2024).
neuroblastoma (2 papers, 2022 to 2025). Neuroblastoma (NB) is the most common solid, extracranial childhood tumor. "Further, THAP1 ChIP-Seq analysis in neuronal cells overexpressing THAP1 revealed that THAP1 is able to bind and activate promoter regions of different SOD2 isoforms in SK-N-AS human neuroblastoma cells." (PMID 38835919, 2022). "To investigate whether THAP1 similarly regulates proteasome activity in neuronal cells, we performed THAP1 knockout in SH-SY5Y cells, a human neuroblastoma-derived cell line." (PMID 39952963, 2025).
Anxiety (1 paper, 2022). Intense feelings of nervousness, tension, or panic often arise in response to interpersonal stresses. "Those involving THAP1 (n = 1) and TOR1A (n = 1) were linked with myelopathies, while SGCE variants (n = 2) were associated with depression, anxiety and myoclonus, and hemiplegia for the single overlapping TH variant." (PMID 35925398, 2022).
atherosclerosis (1 paper, 2022). A disease characterized by the build-up of fatty material and calcium deposition in the arterial wall resulting in partial or complete occlusion of the arterial lumen. "We hypothesized that circTEX14 may play an important role in regulating atherosclerosis via the circTEX14/miR-6509-3p/THAP1 axis." (PMID 35635088, 2022). "Furthermore, serum THAP1 mRNA was significantly decreased in atherosclerosis patients compared with the healthy volunteers." (PMID 35635088, 2022). "CircTEX14 inhibited proliferation and enhanced apoptosis of ox-LDL-stimulated VSMCs via modulating miR-6509-3p/THAP1 and might be useful in atherosclerosis treatment." (PMID 35635088, 2022). "Moreover, serum THAP1 mRNA was significantly decreased in atherosclerosis patients when compared with healthy volunteers." (PMID 35635088, 2022). "In this study, we hypothesized that circTEX14 may play an important role in regulating atherosclerosis via the circTEX14/miR-6509-3p/THAP1 axis and explored the exact role of circTEX14 in the cardiovascular system." (PMID 35635088, 2022). "However, the role of THAP1 in atherosclerosis is still unknown." (PMID 35635088, 2022). "In conclusion, circTEX14 inhibited proliferation and enhanced apoptosis via modulating miR-6509-3p/THAP1 in ox-LDL-stimulated VSMCs and might be a useful target for atherosclerosis treatment." (PMID 35635088, 2022).
breast carcinoma (1 paper, 2022). "THAP1 has been associated with DYT6 dystonia, THAP5 and THAP1 have been linked to apoptosis, the LRRC49/THAP10 bidirectional gene pair is involved in breast cancer, and THAP11 has been implicated in colon and gastric cancers." (PMID 35893234, 2022).
chordoma (1 paper, 2023). Chordomas are rare malignant tumors arising from embryonic remnants of the notochord in axial skeleton. "We included an additional gene for validation, THAP1, that is commonly essential across all cancer cell lines, yet whose loss has a greater degree of viability reduction in chordoma cell lines compared to non-chordoma cell lines." (PMID 37024492, 2023).
Glutaric Aciduria type 1 (1 paper, 2023). "The genetic dystonias were associated with the following genes: TOR1A, THAP1, SGCE, KMT2B, HPRT1 (Lesch Nyhan disease), PANK2 and GCDH (Glutaric Aciduria type 1)." (PMID 36445406, 2023).
Truncal dystonia (1 paper, 2023). Truncal dystonia is a form of focal dystonia (see this term), characterized by involuntary back arching often associated with pain and severe motor disability. "One patient from India with a novel THAP1 frameshift deletion mutation (c.208-209delAA; p.K70VfsX15) also showed a positive response to GPi DBS even after ten years, with particular response of lower limb and truncal dystonia." (PMID 37637848, 2023).
cancer (4 papers, 2021 to 2025). A tumor composed of atypical neoplastic, often pleomorphic cells that invade other tissues. "DepMap data demonstrates that disruption of THAP1 is broadly lethal across cancer cell lines." (PMID 39929834, 2025).
neurologic disease (3 papers, 2014 to 2025). "The presence of a “neuronal-specific” species has profound implications for how mutations may differentially affect Thap1 function in neurons relative to peripheral organs, thereby leading to a neurologic disease." (PMID 25231164, 2014). "A wide range of autosomal dominant mutations distributed throughout the THAP1 coding sequence give rise to DYT-THAP1 dystonia, an early-onset neurological disorder characterized by involuntary muscle contractions and movements causing abnormal and painful posturing." (PMID 39929834, 2025). "The existence of a “neuron-specific” Thap1 species that binds DNA has significant implications when thinking about how mutations in a ubiquitously expressed gene result in a neurologic disease without obvious pathophysiology in other organs." (PMID 25231164, 2014).
infection (2 papers, 2014 to 2025). The state of being infected such as from the introduction of a foreign agent such as serum, vaccine, antigenic substance or organism. "The resulting site-saturation mutagenesis library was packaged into lentiviral particles and introduced into THAP1 KO PPSMB5-GFP reporter cells at low multiplicity of infection, ensuring single-copy expression." (PMID 39929834, 2025). "For all three silencing vectors, particularly #21, multiplicity-of-infection (MOI) and time to harvesting after transduction were limited by cell death, leading us to hypothesize that complete elimination of Thap1 may be lethal to primary, post-mitotic neurons." (PMID 25231164, 2014).
tumor (2 papers, 2017 to 2022). "It is also clear that a number of the candidate drivers including MXI1, SIN3A, THAP1 and ATF3 are down-regulated in PRAD tumours." (PMID 28592290, 2017).
THAP1 also shares sentences with these, for which no sentence is quoted: cervical dystonia (4 papers); laryngeal dystonia (3); movement disorder (3); Adult onset (1); Alzheimer disease (1); blepharospasm (1); depression (1); fragile X syndrome (1); Friedreich ataxia (1); gastric cancer (1); inherited dystonia (1); Lesch Nyhan disease (1); myelopathies (1); neuromuscular disease (1); schizophrenia (1); spinocerebellar ataxias 1 (1); viral infection (1).